PSMB6 (proteasome 20S subunit beta 6)
Diseases named in the same sentence as PSMB6 in open-access papers:
PSMB6 is named in the same sentence as 45 diseases in open-access papers, as found by Europe PMC text mining. Sharing a sentence is not in itself a finding about the gene and the disease. The quoted sentences say what the papers report.
myeloma (5 papers, 2021 to 2025). "In myeloma, shared SNPs in PSMB6 and PSMB9 were associated with a decreased response to bortezomib therapy, without affecting survival, demonstrating how germline variation can influence IP-related therapeutic effects." (PMID 41293269, 2025). "LOH of the proteasome 20S Subunit Beta 6 (PSMB6), located at 17p13.2, also results in haploinsufficiency, and in myeloma the STAT3 inhibitor, stattic, is reported to inhibit PSMB6 protein function to restore sensitivity to the proteasome inhibitor, bortezomib." (PMID 39966556, 2025). "Although the roles of PSMC gene mutations in cancer remain unstudied, multiple mutations in other proteasome family genes, i.e., PSMB5, PSMB6, and PSMB7, are associated with the myeloma cell survival." (PMID 35938038, 2022). "PSMB6 regulated proteasome structure and function, variations in which affected the treatment of multiple myeloma." (PMID 34721732, 2021).
lung carcinoma (4 papers, 2021 to 2024). "Three other drugs (SJ‐172550 for MDM4, nutlin‐3 for MDM2/MDM4, and carfilzomib for PSMA6 and PSMB6) showed improved IC50 values when used as a monotherapy but increased efficacy when used in combination with erlotinib on NCI‐H820 lung cancer cell lines." (PMID 33188726, 2021). "Furthermore, both RT-qPCR and Western blot analyses indicated that the expression of PSMB6 was significantly elevated in the lung cancer cell lines A549 and H1299 compared to the normal lung epithelial cell line B2B (p < 0.05)." (PMID 39507618, 2024). "In addition, PSMB6 is upregulated in hypoxia models, lung cancer, and mesenchymal thyroid cancer." (PMID 34868920, 2021).
COVID-19 (3 papers, 2022 to 2024). A disease caused by infection with severe acute respiratory syndrome coronavirus 2. "Interestingly, PSMB5, PSMB6, and PSMB7 also did not reveal a significant difference between COVID-19 patients and HC, suggesting an overexpression of the immunoproteasome rather than constitutive proteasome." (PMID 35327634, 2022).
lung adenocarcinoma (3 papers, 2021 to 2024). A carcinoma that arises from the lung and is characterized by the presence of malignant glandular epithelial cells. "This indicates that PSMB6 is an important regulatory factor closely associated with the occurrence and development of lung adenocarcinoma." (PMID 39507618, 2024). "In this study, we identified a substantial elevation in the levels of PSMB6 within lung adenocarcinoma tissues, and this enhanced expression was linked to a diminished prognosis for the patients." (PMID 39507618, 2024). "Our research indicates that high expression of PSMB6 is associated with poor immune infiltration and prognosis, while knocking down PSMB6 promotes apoptosis in lung adenocarcinoma cells and inhibits their proliferation, metastasis, and invasion." (PMID 39507618, 2024). "Flow cytometry results indicated that the apoptosis rate of PSMB6 knockdown A549 and H1299 cells was significantly higher than that of the control group (p < 0.01), further validating the role of PSMB6 in resisting apoptosis in lung adenocarcinoma cells." (PMID 39507618, 2024). "This suggests a potential close association between PSMB6 and the MAPK pathway in promoting the growth and specialization of lung adenocarcinoma cells." (PMID 39507618, 2024). "This study found that PSMB6 is relatively highly expressed in lung adenocarcinoma tissues and lung adenocarcinoma cells." (PMID 39507618, 2024). "To further investigate the impact of PSMB6 on the apoptosis and proliferation of lung adenocarcinoma cells, we established PSMB6 knockdown A549 and H1299 cell lines through transient transfection (p < 0.01)." (PMID 39507618, 2024). "By analyzing the TCGA database, we discovered a positive correlation between the expression of PSMB6 and tumor growth trends, and lung adenocarcinoma patients with elevated PSMB6 expression levels had a worse prognosis." (PMID 39507618, 2024). "In vitro experiments demonstrated that knocking down the expression of PSMB6 inhibited the proliferation, invasion, and metastasis of lung adenocarcinoma cells, while promoting their apoptosis." (PMID 39507618, 2024). "We utilized data from the TCGA database to investigate the role of PSMB6 in lung adenocarcinoma (LUAD)." (PMID 39507618, 2024). "Overall, our findings suggest that PSMB6 could remarkably influence the management and treatment of lung adenocarcinoma, opening new avenues for targeted immunotherapeutic strategies." (PMID 39507618, 2024). "However, the precise role of PSMB6 in the immunoregulatory processes within lung adenocarcinoma (LUAD) is yet to be elucidated." (PMID 39507618, 2024). "Additionally, in vitro experiments demonstrated that knockdown of PSMB6 inhibits the proliferation, migration, and invasion of lung adenocarcinoma cells while promoting their apoptosis." (PMID 39507618, 2024). "We next explored the effect of PSMB6 on the migration and invasion of lung adenocarcinoma cells." (PMID 39507618, 2024). "This suggests that PSMB6 may help promote the growth of lung adenocarcinoma cells by reducing the number of immune cells, such as CD8+ T cells and NK cells." (PMID 39507618, 2024). "This suggests that PSMB6 may promote the proliferation and migration of lung adenocarcinoma cells by regulating the EMT process." (PMID 39507618, 2024). "This further confirms the promoting role of PSMB6 in the metastasis of lung adenocarcinoma cells." (PMID 39507618, 2024). "This suggests that PSMB6 may alter the release of cytokines within the immune microenvironment by influencing leukocyte proliferation and cellular activation involved in immune responses, ultimately impacting the activity of lung adenocarcinoma cells." (PMID 39507618, 2024). "Seven other 26S/20S proteasome subunits were isolated (q < 0.05; PSMD12, PSMB4, PSMA6, PSMB6, PSMC1, PSMD3, and PSMB3), illuminating the importance of the 26/20S proteasome integrity in lung adenocarcinoma genome maintenance." (PMID 34070461, 2021).
lung adenocarcinoma (continued). "Using immunohistochemistry, the expression levels of PSMB6, HSPA9, DUT, CDK7, and PLK1 were found to be higher in lung adenocarcinoma tissues of patients, while the expression of FOLR2 was low, which was consistent with survival prediction." (PMID 34721732, 2021). "We found that the expression of CD28, CD80, andCD86 was markedly reduced, suggesting that PSMB6 may decrease their expression to reduce the binding between CD80/CD86 and CD28, ultimately leading to immune evasion in lung adenocarcinoma cells." (PMID 39507618, 2024). "Combined with the observation that the PSMB6 high expression group had a lower immune score, we speculate that PSMB6 may influence the immune microenvironment through the EMT pathway, thereby promoting the proliferation and invasion of lung adenocarcinoma." (PMID 39507618, 2024). "Recent studies have shown that the proteasome is closely related to EMT in the development of gastric cancer, but the interaction between PSMB6 and EMT in lung adenocarcinoma has not been reported." (PMID 39507618, 2024).
Autoimmunity (2 papers, 2011 to 2025). The occurrence of an immune reaction against the organism's own cells or tissues. "Moreover, transcriptomic profiling of human pancreatic alfa-cells has demonstrated enrichment of proteasome-related genes, including PSMB6, suggesting that enhanced proteasomal activity may mitigate endoplasmic reticulum (ER) stress and unfolded protein responses during autoimmunity." (PMID 41441015, 2025).
diabetes (2 papers, 2020 to 2025). "Nevertheless, experimental and transcriptomic evidence support a potential role of PSMB6 in diabetes pathophysiology." (PMID 41441015, 2025). "In the group enriched with diabetic patients (6 out of 9 patients), seven proteasome genes (PSME4, PSMA7, PSMB4, PSMB6, PSMC4, PSMD7 and PSMD8) and three genes previously associated with common diabetes (SNX17, PARK7/DJ-1 and ATP5B) were highly expressed." (PMID 32302349, 2020).
gastric cancer (2 papers, 2022 to 2024). A primary or metastatic malignant neoplasm involving the stomach. "Similarly, subunits PSMB1 and PSMB6 were significantly enriched in serum exosomes derived from metastatic gastric cancer patients." (PMID 35693739, 2022).
soft tissue sarcoma (2 papers, 2017 to 2024). A malignant neoplasm arising from muscle tissue, adipose tissue, blood vessels, fibrous tissue, or other supportive tissues excluding the bones. "Additionally, GUSB and PSMB6 were found to be the most stably expressed reference genes in canine soft tissue sarcomas, as determined using geNorm." (PMID 39335311, 2024). "Reference genes stably expressed in canine soft tissue sarcoma are β-Glucuronidase (GUSB) and proteasome subunit, beta type, 6 (PSMB6); while in canine mammary gland tumors were a combination of hypoxanthine-phosphoribosyl transferase, ATP-synthase subunit 5B, ribosomal protein L32 and ubiquitin." (PMID 29178874, 2017).
thyroid cancer (2 papers, 2007 to 2024). "The reason for choice of PSMB6 is unclear in breast cells/tumor, but high expression is also found in thyroid cancer although not much is known about its role in carcinogenesis." (PMID 17883861, 2007).
autoimmune type 1 diabetes (1 paper, 2011). Autoimmune disease wherein the body's own immune system attacks and destroys the cells within the pancreas that produce insulin. "Interestingly, PSMB6 is replaced by an alternative proteasome subunit, LMP2, to form an “immunoproteasome” in response to interferon signaling, and has been identified as a candidate gene contributing to autoimmune type-1 diabetes in mice." (PMID 22241984, 2011).
breast tumors (1 paper, 2023). "However, downregulated secretome markers FN1, PSMB6, PRDX4, and PEA15 are also upregulated at the mRNA level in breast tumors." (PMID 37128318, 2023). "PSMB6 and MYL6B have the same expression in breast tumors and normal tissues." (PMID 37128318, 2023).
childhood cancer (1 paper, 2019). "We propose that PSMB6, PGGT1B, UBQLN2 and UQCR2 are housekeeping genes with low expression in childhood cancer." (PMID 31108950, 2019).
glioma (1 paper, 2021). A benign or malignant brain and spinal cord tumor that arises from glial cells (astrocytes, oligodendrocytes, ependymal cells). "This study found the prognostic predictive values of the hypoxia-related genes PSMB10, PSMD12, UBB, PSMA5, and PSMB6 for glioma and provided ideas and entry points for the progress of hypoxia-related glioma." (PMID 34868920, 2021). "In the present study, PSMA5 and PSMB6 were found to be highly expressed in gliomas, while PSMB10 was found to be lowly expressed by integrating the TCGA and GTEx databases’ glioma sample analyses." (PMID 34868920, 2021). "Univariate and multifactorial COX regression analyses were used to determine that PSMB10, PSMD12, UBB, PSMA5, and PSMB6 may be independent prognostic factors for gliomas." (PMID 34868920, 2021). "Notably, PSMB10, PSMD12, UBB, PSMA5, and PSMB6 were found to be independent prognostic predictive markers for glioma." (PMID 34868920, 2021). "PSMB10, PSMD12, UBB, PSMA5, and PSMB6 were found to be independent predictors of glioma prognosis." (PMID 34868920, 2021). "The results showed that PSMB6, PSMA5, UBB, and PSMD12 were highly expressed in the glioma tissues, while PSMB10 was lowly expressed in the glioma tissues compared with the normal tissues." (PMID 34868920, 2021). "The results showed that PSMB6, PSMA5, UBB, and PSMD12 were significantly downregulated, and PSMB10 was significantly upregulated in gliomas." (PMID 34868920, 2021). "In addition, PSMB6, PSMA5, UBB, and PSMD12 were lowly expressed, while PSMB10 was highly expressed, in the TCGA and GTEx integrated glioma samples and normal samples, which were verified through protein expression levels in the Human Protein Atlas database." (PMID 34868920, 2021).
hepatocellular carcinoma (1 paper, 2026). A malignant tumor that arises from hepatocytes. "Functional validation further confirmed that siRNA-mediated knockdown of PSMB5 and PSMB6 significantly impaired proliferation across multiple hepatocellular carcinoma cell lines." (PMID 42280256, 2026).
hypersomnia (1 paper, 2023). A sleep disorder characterized by excessive sleepiness. "Six (GPX4, PSMB5, PSMB6, PRDX5, ASNA1, EIF4H) out of seven hub genes were associated with the expression of insomnia/hypersomnia only in females, while UROD was the only hub gene common to both sexes." (PMID 37884562, 2023).
pancreatic adenocarcinoma (1 paper, 2024). "However, in pancreatic adenocarcinoma (PAAD), elevated levels of PSMB6 expression correlate with a more favorable prognosis." (PMID 39507618, 2024).
renal cell carcinoma (1 paper, 2023). "These 27 CTTs including 8 genes CTNNA1, PSMB6, PSMD12, SESN2, SLC22A2, UBE2J2, and NAE1 appeared in the SL pairs of renal cell carcinoma in previous literature studies." (PMID 38074121, 2023).
sarcoma (1 paper, 2023). A usually aggressive malignant neoplasm of the soft tissue or bone. "Particularly, the expression levels of other proteasome pathway genes, including PSMC1, PSMB6, PSMC2, and PSMB10 seemed to be differentially expressed in MFS/US sarcomas." (PMID 37185612, 2023).
tumor (17 papers, 2007 to 2024). "We observed that the low expression group of PSMB6 and the low-risk group showed higher immune cell infiltration and lower tumor purity." (PMID 39507618, 2024). "Recent research has indicated that proteasome 20S subunit 6 (PSMB6) may be closely associated with anti-apoptotic pathways, and proliferation transduction signals in tumor cells of different tumors." (PMID 39507618, 2024). "The results indicated that PSMB6 expression was significantly higher in tumor tissues compared to normal tissues (p < 0.01)." (PMID 39507618, 2024). "The results showed that the expression of PSMB6 in 30 LUAD tumor samples was significantly higher than that in paired normal samples (p < 0.01)." (PMID 39507618, 2024). "This analysis focused on the differences in PSMB6 expression between normal and tumor tissues, as well as its relationships with single nucleotide variants (SNV), copy number variations (CNV), cancer stages, and patient survival." (PMID 39507618, 2024). "Although the mRNA levels in PSMB6 saw a significant increase as tumor stage increased, the mRNA levels in tumors of either stage were lower than those expressed in normal renal tissues." (PMID 35693739, 2022). "Analysis of thousands of tumor samples from The Cancer Genome Atlas (TCGA) reported an increased expression of proteasomes such as PSMB6, PSMB7, and PSMD2 in most cancer types." (PMID 31877708, 2019). "Considering the crucial role of epithelial-mesenchymal transition (EMT) in tumor progression and metastasis, we conducted Western blot analysis to evaluate the expression levels of E-Cadherin and N-Cadherin in A549 and H1299 cells after PSMB6 knockdown." (PMID 39507618, 2024). "In the present study, decreased expression of PSMB6 mRNA was found in ccRCC tissues compared to normal tissues, but a positive correlation between the PSMB6 mRNA levels and patients' individual cancer stages and tumor grades was confirmed." (PMID 35693739, 2022). "Therefore, overexpression of PSMB6 might promote tumor growth through immunosuppression induced by the insufficiency of PSMB9." (PMID 35693739, 2022). "Second, conducting animal experiments to elucidate the role of PSMB6 in LUAD, particularly its impact on the tumor immune microenvironment, is essential." (PMID 39507618, 2024). "After systematic data curation, four upregulated (YWHAB, TXNDC12, MYL6B, SFN) and four downregulated (FN1, PSMB6, PRDX4, PEA15) markers in miRNA-overexpressed tumor secretomes were identified." (PMID 37128318, 2023). "The overexpression of PSMB6, HSPA9, DUT, CDK7, and PLK1 was seen in resected tumor tissues compared with adjacent normal tissues, while FOLR2 was expressed more in normal tissues." (PMID 34721732, 2021). "This indicates that PSMB6 may serve as a pivotal factor within the TIME by reducing immune cell infiltration, thereby aiding tumor cells in immune evasion." (PMID 39507618, 2024). "In the analysis of gene expression in whole proteasomes including PSMB5 (β5), PSMB8 (iβ5), PSMB7 (β2), PSMB10 (iβ2), PSMB6 (β1), and PSMB9 (iβ1), these genes alternated or showed only slight in their expression following silencing of PSMB5 or PSMB7 in three tumor cells." (PMID 29515784, 2018).
cancer (13 papers, 2010 to 2026). A tumor composed of atypical neoplastic, often pleomorphic cells that invade other tissues. "Collectively, this study prioritizes PSMB5 and PSMB6 as consistently associated functional biomarkers that integrate genetic dependency and immune context, providing a data-driven framework for stratifying proteasome-targeted therapeutic strategies across cancers." (PMID 42280256, 2026). "On the other hand, Psmb3, Psmb6, and Psmb8 are the members of the proteasome subunit and have been found in most cancers." (PMID 33919822, 2021). "We evaluated the pan-cancer expression profile of PSMB6 using data from the TCGA database." (PMID 39507618, 2024). "Besides, mRNA levels of PSMB3 and PSMB6 in normal renal tissues were found to be higher than those in cancer tissues." (PMID 35693739, 2022). "Additionally, these results show that PSMB6 could serve as a prognostic marker and therapeutic target for malignant tumors, providing a new avenue for targeting the proteasome." (PMID 39507618, 2024). "Moreover, the expression levels of proteasome genes, such as PSMB6, have been observed to increase in many types of cancers, suggesting that PSMB6 could potentially serve as a molecular therapeutic target." (PMID 39507618, 2024). "In comparison to other cancer types, STS showed high expression of PSMB5, PSMB6 and PSMB7, the subunits of the constitutive proteasome and low levels of PSMB8, PSMB9 and PSMB10, the subunits specific to immunoproteasomes." (PMID 32851475, 2021). "Based on transcriptomic analyses of thousands of samples from The Cancer Genome Atlas, we report that expression of constitutive proteasome (CP) genes (PSMB5, PSMB6, PSMB7) and immunoproteasome (IP) genes (PSMB8, PSMB9, PSMB10) is increased in most cancer types." (PMID 27659694, 2016).
PSMB6 also shares sentences with these, for which no sentence is quoted: Multiple Myeloma (3 papers); melanoma (2); neurodevelopmental disorder (2); Alzheimer disease (1); and Metabolism Syndrome (1); autism (1); Bladder Cancer (1); breast carcinoma (1); Cachexia (1); dentatorubral-pallidoluysian atrophy (1); Dystonia (1); endometrial cancer (1); Esophageal Carcinoma (1); fibrosis (1); infection (1); insomnia (1); Liver abscess (1); Lung Squamous Cell Carcinoma (1); metastatic melanoma (1); neurological disorders (1); plague (1); prostate carcinoma (1); schizophrenia (1); skin infection (1); uterine corpus endometrial carcinoma (1).